POSTN (periostin)
Diseases named in the same sentence as POSTN in open-access papers (continued):
Sharing a sentence is not in itself a finding about the gene and the disease.
craniosynostosis (continued). "Although our findings showed a regulatory role of the Periostin/BMP1 axis in both mouse models and SMSC models for craniosynostosis, we need to further correlate these findings with clinical data related to human diseases." (PMID 38369459, 2024). "This study aims to further explore the functions and regulatory mechanisms of Periostin and BMP1 in craniosynostosis, analyze the Periostin/BMP1 axis in the proliferation and osteogenic differentiation of SMSCs, and explore its interaction with mutations in the TWIST1 gene." (PMID 38369459, 2024). "The in vivo results demonstrated that periostin-treated Twist1+/− mice showed patent coronal sutures in comparison with non-treated Twist1+/− mice which have coronal craniosynostosis." (PMID 29665811, 2018).
cutaneous T-cell lymphoma (2 papers, 2020). "In cutaneous T-cell lymphomas, periostin is expressed mainly in early disease and appears to increase expression of Th1 chemokines, which might attract Th1-dominant antitumor CD8 T cells." (PMID 32398793, 2020).
depression (2 papers, 2016 to 2023). "The aim of this study was to investigate the potential antidepressant and anxiolytic effects of vitamin C and vitamin D in a stress-induced mouse model of depression, while also exploring the association between these effects and the levels of circulating NOx, periostin, and FKBPL." (PMID 37375593, 2023). "Under stress-induced depression, periostin levels rose, and only escitalopram brought them back down to normal." (PMID 37375593, 2023). "In the current study, stress-induced depression was found to increase periostin, and only escitalopram normalized it." (PMID 37375593, 2023). "The study confirms the role of periostin as an important mediator in depression and its normalization by escitalopram." (PMID 37375593, 2023). "In conclusion, the study establishes the potential antidepressant effects of vitamin C and vitamin D mediated by NOx and FKBPL levels, as well as the crucial role of periostin in depression." (PMID 37375593, 2023). "Additionally, our study uncovered elevated levels of periostin in stress-induced depression, which were only restored to normal levels by escitalopram, suggesting a potential role for periostin in mood disorders." (PMID 37375593, 2023). "Furthermore, periostin was observed to increase in stress-induced depression, and only escitalopram was effective in normalizing its levels." (PMID 37375593, 2023). "Overall, our findings suggest that vitamin C, vitamin D, and escitalopram may possess antidepressant properties mediated by NOx and FKBPL levels, while emphasizing the potential significance of periostin in the context of depression." (PMID 37375593, 2023). "Future studies should examine NOx, periostin, and FKBPL in the hippocampus and prefrontal cortex, two critical brain regions involved in depression, to provide a full picture of how these biomarkers are related to depressive symptoms." (PMID 37375593, 2023).
diffuse large B-cell lymphoma (2 papers, 2020 to 2024). "Finally, certain lymphoproliferative diseases are also associated with expression of COL6A1, COL18A1, MMP3 and TIMP1, and a subset of patients with diffuse large B cell lymphoma and adverse prognosis show decreased expression of POSTN, SPARC, COL1A1, COL3A1,CSTK, MMP9 and LAMB3." (PMID 33379263, 2020).
ductal carcinoma in situ (2 papers, 2021 to 2022). "To elaborate, periostin expression was elevated in a stepwise manner from normal tissue to ductal carcinoma in situ (DCIS) tissue and invasive breast cancer (IBC) tissues." (PMID 36224629, 2022). "The matricellular protein periostin (PN), secreted mainly by CAFs, binds to cancer cell surface receptors activating progression in invasive ductal breast carcinoma (IDC), showing increased PN levels compared to ductal carcinoma in situ (DCIS)." (PMID 34337083, 2021).
emphysema (2 papers, 2018 to 2022). "Likewise, the role of periostin in emphysema is not yet fully understood." (PMID 36678775, 2022).
endometriosis (2 papers, 2016 to 2022). The growth of functional endometrial tissue in anatomic sites outside the uterine body. "In our previous study, we observed significantly higher expression of periostin in the ectopic and eutopic endometrium of endometriosis." (PMID 27034956, 2016). "Our previous study showed significantly higher expression of periostin in the eutopic and ectopic endometrium of endometriosis." (PMID 27034956, 2016). "In line with this, we demonstrated that periostin facilitated the progress of endometriosis by enhancing the adhesion, migration, and invasion of ESCs." (PMID 27034956, 2016). "Although endometriosis shares many characteristics with tumors, little is known about the role of periostin in endometriosis." (PMID 27034956, 2016). "In the present study, we assessed the effect of periostin on the migration and invasion abilities of EECs of endometriosis and demonstrated that periostin indeed enhanced the migration and invasion abilities of EECs." (PMID 27034956, 2016). "However, the therapeutic effect of targeting periostin on endometriosis remains to be investigated in the future." (PMID 27034956, 2016). "Playing a pivotal role in the pathogenesis of endometriosis, periostin may be a new clinical therapy target for endometriosis." (PMID 27034956, 2016). "Additionally, we demonstrated that periostin facilitated endometriosis by enhancing the migration, adhesion, and invasion of endometrial stromal cells (ESCs)." (PMID 27034956, 2016). "Although periostin was confirmed to facilitate the pathogenesis of endometriosis by enhancing the migration, invasion, and adhesion of human endometrial stromal cells (ESCs), its effect on the endometrial epithelial cells (EECs) is still unknown." (PMID 27034956, 2016). "Drugs repressing the expression or inhibiting the function of periostin may suppress the progress and recurrence of endometriosis." (PMID 27034956, 2016). "Playing critically key roles in the EMT process during the pathogenesis of endometriosis, periostin may be a new clinical therapy target for endometriosis." (PMID 27034956, 2016). "Given that endometriosis behaves malignantly by penetrating and developing elsewhere like tumor metastasis, we herein hypothesize that periostin may facilitate endometriosis by inducing the EMT of EECs." (PMID 27034956, 2016). "Therefore, periostin played crucial roles in the pathogenesis of endometriosis by facilitating the EMT of EECs." (PMID 27034956, 2016). "Given its critical role in the pathogenesis of endometriosis, periostin may be a promising therapy target for endometriosis." (PMID 27034956, 2016). "Thus, we propose that periostin may facilitate the EMT of EECs in the pathogenesis of endometriosis." (PMID 27034956, 2016). "Consistent with this, our previous study demonstrated that periostin enhanced the adhesion, migration, and invasion of ESCs through ILK-Akt pathway in endometriosis." (PMID 27034956, 2016). "However, the effect of periostin on the EECs of endometriosis is still unknown." (PMID 27034956, 2016). "In our previous study, we detected the concentration of periostin in peritoneal washing fluids of patients with and without endometriosis, which was 48.32 ng/mL and 22.29 ng/mL, respectively (data not published yet)." (PMID 27034956, 2016).
hip fracture (2 papers, 2022 to 2023). Traumatic or pathological injury to the hip in which the continuity of either the femoral head, femoral neck, intertrochanteric or subtrochanteric regions is broken. "Increased serum POSTN levels in hip fractures in older Chinese women are also reported during the early healing phase, suggesting that POSTN plays a role in bone repair." (PMID 38020106, 2023). "J. Yan et.al and M. Farrokhiet.al found that higher serum periostin levels were presenting with acute hip fracture, implying periostin’s healing function during early phase." (PMID 35327993, 2022).
injury (2 papers, 2022). Damage inflicted on the body as the direct or indirect result of an external force, with or without disruption of structural continuity. "Molecular pathways such as cAMP, MAPK, JAK/STAT, ATF3/CREB, BMP/SMAD, AKT/mTORC1/p70S6K, PI3K/AKT, GSK-3β/CLASP, BDNF/Trk, Ras/ERK, integrin/FAK, RhoA/ROCK/LIMK, and POSTN/integrin are activated after nerve injury and are considered significant players in axonal regeneration." (PMID 36551942, 2022).
intracerebral haemorrhage (2 papers, 2018 to 2021). "In addition, a recent study reported that serum periostin levels were significantly increased in patients with intracerebral haemorrhage (ICH) within 6 h after ICH compared with controls, and its levels were consistently increased within almost 24 h after ICH16." (PMID 30082879, 2018).
ischemic stroke (2 papers, 2021 to 2022). A stroke disorder caused by obstruction of blood flow to the brain, due to thrombotic (local blood clot formation) or embolic (due to a blood clot or other material traveling from another site) event. "We aimed to measure serum periostin levels in the hyperacute phase of ischemic stroke to explore its predictive power in identification of patients with poor collaterals (ASPECT < 6)." (PMID 36010292, 2022). "In the present study, we aimed to measure serum periostin levels at admission in patients with acute ischemic stroke and investigate whether it has predictive value or decision-making power in very early ischemic stroke by helping to estimate core volume." (PMID 36010292, 2022). "Thus, serum periostin level at the time of admission indirectly indicates the quality of the collateral network in the acute phase of ischemic stroke." (PMID 36010292, 2022). "In our study, we found that serum periostin concentration is an independent predictor of ASPECT < 6 calculated on admission, and this finding indicates that periostin could reflect the extent of early brain injury in hyperacute stage of ischemic stroke." (PMID 36010292, 2022). "First, data about the changes of circulating periostin concentrations during the progression of ischemic stroke were not reported." (PMID 36010292, 2022).
kidney tumor (2 papers, 2007 to 2021). "In breast and kidney tumors, the difference in periostin expression was not significant due to the highly variable POSTN expression levels measured in both normal and tumoral samples." (PMID 18086302, 2007).
knee osteoarthritis (2 papers, 2021 to 2023). "Additionally, lower serum POSTN levels have been linked with the prevalence of knee osteoarthritis and the risk of its development and progression in women." (PMID 38020106, 2023). "Additionally, increased serum POSTN levels have been noted in patients with AS with increased disease activity and systemic inflammation and in advanced groups of OPLL, and the levels positively correlated with the radiological severity of knee osteoarthritis." (PMID 38020106, 2023).
left ventricular hypertrophy (2 papers, 2014 to 2015). Enlargement of the LEFT VENTRICLE of the heart. "In both animal and human models, periostin is closely associated with pressure overload-induced left ventricular hypertrophy (LVH) and LVH regression." (PMID 26281830, 2015). "Periostin showed close relationship with pressure overload induced maladaptive left ventricular hypertrophy, which was highly associated with end-stage heart failure." (PMID 24586384, 2014).
lymphedema (2 papers, 2025). Excess fluid collection in tissues, causing swelling. "Further expression analysis revealed that only four of these genes(POSTN, ASPN, FMOD, and MFAP5) exhibited statistically significant differential expression between lymphedema and control tissues, indicating their potential biological relevance in the fibrosis pathogenesis of lymphedema." (PMID 40881699, 2025).
medulloblastoma (2 papers, 2019 to 2020). A malignant, invasive embryonal neoplasm arising from the cerebellum. "Next, we moved our attention to genes already related to medulloblastoma based on the literature and validated some of them, such as POSTN, BOC, VCAM1, and TP63 among the downregulated genes and ANKRD1, THBS1, NRG1, PTHLH, and HBEGF among the upregulated ones in DAOY and D283Med cells." (PMID 32316671, 2020).
metastasis (2 papers, 2022). The spread or migration of cancer cells from one part of the body (where they first appeared) to another. "Our analysis was limited to four genes, ASPN, POSTN, SPARCL1, and MCAM, which we determined as potential markers of stromal activation in a xenograft model of PC bone metastasis." (PMID 36185585, 2022).
mitral valve disease (2 papers, 2015 to 2019). "This included cilia defects responsible for disorganization of valve interstitial cells within the leaflets and excess secretion of hyaluronan, collagen I and periostin, a hallmark of mitral valve prolapse." (PMID 31028265, 2019). "Here, we examine VIC phenotypes in established mouse models of mitral valve disease using SMA, Periostin, Twist1 and Vimentin expression." (PMID 26527432, 2015).
myxoma (2 papers, 2024 to 2025). A benign soft tissue neoplasm characterized by the presence of spindle and stellate cells, lobulated growth pattern, and myxoid stroma formation. "Fibroblasts within myxomas exhibit an activated state, characterized by elevated expression of well-known activated fibroblast markers 18such as POSTN, NOX4, FAP, and COL1A2." (PMID 39090109, 2024).
neurofibroma (2 papers, 2021 to 2022). An intraneural or extraneural neoplasm arising from nerve tissues and neural sheaths. "SCP-like cells are also marked by elevated expression of periostin (Postn), which is also upregulated by neurofibroma NMSCs." (PMID 36134665, 2022).
obstructive sleep apnea (2 papers, 2020 to 2022). "However, the roles of periostin in patients with obstructive sleep apnea (OSA) remain unclear." (PMID 32517742, 2020).
osteitis (2 papers, 2021 to 2025). "Osteritic changes has been proven to be related to CRS severity accompanied with a higher presence of bony remodeling, which could be evaluated by CT, but the association between osteitis and periostin in ECRS needs further researches." (PMID 32954441, 2021). "In this study, we investigated the cellular origin of periostin in the sinonasal mucosa and explored the relationship between Th2 cytokine-induced periostin secretion and osteitis in patients with ECRS." (PMID 40607434, 2025). "A moderate but statistically significant positive correlation was observed between periostin concentrations and osteitis scores (r = 0.4171, P = 0.034; Spearman’s rank correlation)." (PMID 40607434, 2025). "Periostin maintains tissue remodeling homeostasis during chronic inflammatory damage; however, periostin secreted in the nasal mucosa induces osteitis in sinonasal bone." (PMID 40607434, 2025). "Furthermore, periostin concentrations in the nasal tissue were moderately positively correlated with osteitis severity." (PMID 40607434, 2025). "In addition to its role in inflammation and tissue remodeling, periostin has been implicated in bone changes associated with chronic rhinosinusitis (CRS), specifically in osteitis and osteoneogenesis." (PMID 40607434, 2025). "Periostin levels were elevated in ECRS tissues and modestly correlated with osteitis scores." (PMID 40607434, 2025). "Interestingly, recent publications demonstrate that osteitis may be reckoned as a marker of ECRS, which may due to local or systemic mediator of inflammation periostin." (PMID 32954441, 2021).
pancreatic neuroendocrine tumor (2 papers, 2019 to 2022). Pancreatic endocrine tumor, also known as pancreatic neuroendocrine tumor (PNET), describes a group of endocrine tumors originating in the pancreas that are usually indolent and benign, but may have the potential to be malignant. "Moreover, they showed that periostin deficiency also impeded the upregulation of FGF2, an adaptive mechanism previously implicated in pancreatic neuroendocrine tumors evasion from anti-angiogenic therapy." (PMID 30889903, 2019).
Pleural effusion (2 papers, 2010 to 2020). The presence of an excessive amount of fluid in the pleural cavity. "Recent studies have also demonstrated that the expression of periostin can be detected in the pleural effusions of NSCLC patients." (PMID 32719746, 2020).
postmenopausal osteoporosis (2 papers, 2020 to 2021). Metabolic disorder associated with fractures of the femoral neck, vertebrae, and distal forearm. "Therefore, the primary aim of this study was to analyse the role of POSTN in oestrogen-deficiency-related postmenopausal osteoporosis." (PMID 32420385, 2020). "In subsequent research, in vivo Periostin knock-out experiments will be needed to confirm further its importance in the osteogenic effect in postmenopausal osteoporosis rat models." (PMID 34591063, 2021). "Altogether, more in vivo and in vitro studies are necessary to provide new insights into the molecular pathology of Periostin-related postmenopausal osteoporosis." (PMID 34591063, 2021). "In turn, this novel network between POSTN and osteogenic induction during degenerative bone disease may provide novel targets and strategies for the development of alternative therapies and biomarkers for postmenopausal osteoporosis." (PMID 32420385, 2020).
prostate adenocarcinoma (2 papers, 2015 to 2021). "Periostin peritumoral stromal staining is positively associated with prostate adenocarcinoma (TMAs from UCLA)." (PMID 25781169, 2015). "Periostin epithelial cell staining is positively associated with prostate adenocarcinoma (TMAs from UCLA)." (PMID 25781169, 2015). "POSTN and NETO1 were correlated with androgen receptor expression, a main driver of prostate adenocarcinoma progression." (PMID 34133324, 2021).
pseudoexfoliation syndrome (2 papers, 2020 to 2024). "They measured the levels of HSP70, periostin, and irisin in the aqueous fluid of patients with pseudoexfoliation syndrome and cataracts and compared them with the results of a control group (cataract patients without pseudoexfoliation syndrome)." (PMID 38999417, 2024).
pulmonary tuberculosis (2 papers, 2013 to 2020). A bacterial infection that affects the lungs and is caused by Mycobacterium tuberculosis. "Periostin expression was also analyzed in 6 benign lung tumors (including 3 inflammatory pseudotumors and 3 pulmonary tuberculosis), and higher expression was observed at the protein level in the pseudotumors and tuberculosis than in the adjacent and surrounding tissues (P<0.05)." (PMID 24273600, 2013). "In this study, serum levels of interferon gamma (IFN-γ), matrix metalloproteinases 1 and 9 (MMP-1 and MMP-9, respectively), and periostin were compared between 40 pulmonary tuberculosis (PTB) and 28 non-tuberculous pneumonia (non-PTB) patients." (PMID 31917802, 2020).
renal carcinoma (2 papers, 2018 to 2022). A carcinoma arising from the epithelium of the renal parenchyma or the renal pelvis. "POSTN also activates migration and invasion of renal carcinoma via integrin/focal adhesion kinase/JNK signaling pathway." (PMID 30586863, 2018). "High-level expression of POSTN can promote EMT via ILK/AKT/mTOR pathway in renal carcinoma." (PMID 35508298, 2022).
rhinitis (2 papers, 2020 to 2022). An inflammation of the mucous membrane lining the nose, usually associated with nasal discharge. "Therefore, we used HNEpCs to investigate the mechanisms underlying the anti-rhinitis activity of CSLW and found that CSLW significantly inhibited the accumulation of eosinophils and upregulation of periostin, MUC5AC, and ROS in IL-4- and IL-13-stimulated HNEpCs in a concentration-dependent manner." (PMID 36421442, 2022).